CATIP-AS1 (CATIP antisense RNA 1)
Gene: Long non-coding RNA gene on chromosome 2 (218,366,661 to 218,369,099, reverse strand). Ensembl gene ENSG00000225062.
Diseases named in the same sentence as CATIP-AS1 in open-access papers:
CATIP-AS1 is named in the same sentence as 1 disease in open-access papers, as found by Europe PMC text mining. Sharing a sentence is not in itself a finding about the gene and the disease.
CATIP-AS1 shares sentences with these, for which no sentence is quoted: thyroid cancer (1 paper).